RRM2 (ribonucleotide reductase regulatory subunit M2)
Diseases named in the same sentence as RRM2 in open-access papers (continued):
Sharing a sentence is not in itself a finding about the gene and the disease.
head and neck cancer (4 papers, 2014 to 2023). A primary or metastatic malignant neoplasm affecting the head and neck. "In a previous study, we demonstrated that using hydroxyurea to inhibit RRM2 significantly enhanced the chemosensitivity of KB cells (a head and neck cancer cell line) to gemcitabine." (PMID 25213022, 2014).
lymphoma (4 papers, 2020 to 2025). A malignant (clonal) proliferation of B- lymphocytes or T- lymphocytes which involves the lymph nodes, bone marrow and/or extranodal sites. "Meanwhile, RRM2 inhibition acted in synergy with gemcitabine in lymphoma and with a WEE1 inhibitor in H3K36me3-deficient cancers." (PMID 36315425, 2022). "Interestingly, a higher fraction of the Chk1 and Rrm2 transgenic mice developed tumors, primarily lymphomas, compared to WT mice, although this difference was not statistically significant." (PMID 32253367, 2020).
osteosarcoma (4 papers, 2021 to 2025). A usually aggressive malignant bone-forming mesenchymal neoplasm, predominantly affecting adolescents and young adults. "Wefound that among the DNA metabolism-related genes with elevated expressionin osteosarcoma tissue, RRM2 showed a significantly higher expressionin both osteosarcoma cells and osteosarcoma-associated heterogeneousendothelial cells." (PMID 40834268, 2025). "The transfection of RRM2-overexpressing plasmids partially reversed the decrease in the proliferation, migration, and invasion ability of osteosarcoma cells caused by TFRC knockdown." (PMID 40510157, 2025). "This indicates that RRM2 plays a crucial role inthe heterogeneous proliferation of both osteosarcoma cells and osteosarcoma-associatedheterogeneous endothelial cells." (PMID 40834268, 2025). "Our analysis of public databases revealed that RRM2 is overexpressed in osteosarcoma and that this overexpression is associated with poor overall survival in osteosarcoma patients." (PMID 40510157, 2025). "The related mechanisms are illustrated in Figure L. Through flow cytometry,we confirmed that RRM2 overexpression significantly accelerated thecell cycle of both osteosarcoma cells and osteosarcoma-associatedheterogeneous endothelial cells, effectively reversing the effectsof cisplatin." (PMID 40834268, 2025). "Therefore, RRM2 could be a highly significant targetfor simultaneously inhibiting the malignant proliferation of bothosteosarcoma cells and osteosarcoma-associated heterogeneous endothelialcells." (PMID 40834268, 2025). "In the integrated datasets of TARGET-OS (n=88) and GTEx (n=396), RRM2 was also significantly overexpressed in osteosarcoma tissues compared with normal skeletal muscle tissues (P<0.0001)." (PMID 40510157, 2025). "The results showed that in the GSE42352 dataset, the expression of RRM2 in osteosarcoma cell lines (n=19) was significantly greater than that in mesenchymal stem cells (n=12) (P<0.0001)." (PMID 40510157, 2025). "The Westernblot results further confirmed that palmatine reduces RRM2 expressionin both osteosarcoma cells and HVECs and decreases the expressionof cell cycle and DNA damage repair-related proteins, such as cyclinB1, cyclin E1, and CHEK1." (PMID 40834268, 2025). "Targeting osteosarcoma tumor cells and their HVECs inducesDNA damage while inhibiting RRM2 expression, preventing cellular self-repairand creating a positive feedback loop for enhanced therapy." (PMID 40834268, 2025). "Through various experiments, we found that TFRC is generally highly expressed in osteosarcoma cells and affects the proliferation, migration and invasion of osteosarcoma cells by regulating the total intracellular iron level and RRM2 expression." (PMID 40510157, 2025). "We then performed qRT-PCR to assess the expression of five hub genes (TOP2A, CDK1, MAD2L1, AURKA and RRM2) in human normal osteoblast cells and osteosarcoma cells." (PMID 34156352, 2021). "Subsequently, we performed qRT-PCR to measure TOP2A, CDK1, MAD2L1, AURKA and RRM2 expression in human normal osteoblast cells (hFOB 1.19) and osteosarcoma cells (MG63, U208 and 143B)." (PMID 34156352, 2021). "In addition, we used IHC staining to assess the protein expression of TFRC and RRM2 in human osteosarcoma tissues (n=30) and osteoblastoma tissues (n=12) as controls." (PMID 40510157, 2025). "However, to our surprise, IHC experiments showed that RRM2-specific staining was notably weak in both osteosarcoma and osteoblastoma tissues." (PMID 40510157, 2025). "We found that, compared to adjacentnormal tissues, osteosarcoma tumor tissues exhibited an overall highexpression of DNA metabolism-related genes, such as TOP2A, RRM2, andCLSPN, in most samples, indicating active DNA replication, repair,and other metabolic processes in osteosarcoma." (PMID 40834268, 2025).
thymoma (4 papers, 2022 to 2024). A neoplasm arising from the epithelial cells of the thymus. "Moreover, in line with previous studies on mouse thymoma cells exposed to tributyltin oxide, another EDC, we observed positive correlations between some POPs and increased expression of the RRM2 gene, which has been reported to promote EMT through the STAT3 cascade." (PMID 38674005, 2024). "In CESC, ESCA, GBM, LUSC, and thymoma (THYM), RRM2 had a negative correlation with marker genes of immune activating genes, such as VSTR, TNFSF14, TNFRSF14, and STING1." (PMID 36518297, 2022).
acute myeloid leukemia (3 papers, 2016 to 2026). Acute myeloid leukemia (AML) is a group of neoplasms arising from precursor cells committed to the myeloid cell-line differentiation. "For example, RRM2, a subunit of ribonucleotide reductase, was identified as a novel molecular target of AZA in acute myeloid leukemia." (PMID 27036028, 2016). "Indeed, ribonucleotide reductase M2 (RRM2), a subunit of ribonucleotide reductase, was identified as a novel molecular target of AZA in acute myeloid leukemia." (PMID 27036028, 2016).
colorectal adenocarcinoma (3 papers, 2016 to 2021). The most common type of colorectal carcinoma. "Our study showed that RRM2 was associated with disease-free survival of colorectal adenocarcinoma and was an important target gene predicted after tumor treatment." (PMID 33519906, 2020). "We found that among the 12 central genes, CCNA2, MAD2L1, DLGAP5, and AURKA were associated with the overall survival of colorectal adenocarcinoma (P < 0.05), and RRM2 and AURKA were associated with disease-free survival of colorectal adenocarcinoma (P < 0.05)." (PMID 33519906, 2020). "The data from TCGA database (Colorectal Adenocarcinoma: TCGA, Nature 2012) was analyzed to determine the correlation between CREB1 and RRM2 at mRNA level in clinical CRC specimens by the cBioPortal platform." (PMID 27801665, 2016).
invasive ductal carcinoma (3 papers, 2013 to 2020). "Our findings were validated by another study to some extent, and they found DEPDC1, EXO1, RRM2 and some proteins had enhanced expression in the ductal carcinoma in situ and invasive ductal carcinoma." (PMID 31998560, 2020).
liver cirrhosis (3 papers, 2016 to 2021).
lymph node metastasis (3 papers, 2014 to 2023). "And further analysis showed that the RRM2 and CREB1 staining was positively correlated with lymph node metastasis, distant metastasis and advanced TNM stages (p<0.05)." (PMID 27801665, 2016). "Serum RRM2 levels in NSCLC patients were significantly elevated compared to healthy controls and were also associated with distant metastasis and histological type, but not with tumor size or lymph node metastasis." (PMID 37699023, 2023).
malignant glioma (3 papers, 2016 to 2025). A grade III or grade IV glioma arising from the central nervous system. "These interactions underscore the pivotal role that RRM2 plays in the pathology of malignant gliomas, highlighting its importance not only as a marker of poor prognosis but also as a critical target for therapeutic intervention." (PMID 39248068, 2025).
oral cancer (3 papers, 2008 to 2023). "Increased RRM1 and RRM2 activity was identified in highly metastatic tumour cells, whereas overexpression of RRM2 in human oral carcinoma cells was shown to be associated with increased invasive potential, probably through NF-κB and MMP-9." (PMID 18414411, 2008). "One such potential transcription factor is NF-κB, which has been shown to regulate RRM2 expression in gemcitabine-resistant human oral cancer KB cell line." (PMID 26894857, 2016).
rheumatoid arthritis (3 papers, 2023 to 2024). A chronic, systemic autoimmune disorder characterized by inflammation in the synovial membranes and articular surfaces. "Because of its biological function and diagnostic efficacy, RRM2 may serve as a crucial target for ferroptosis related mechanisms in rheumatoid arthritis." (PMID 36717858, 2023). "Studies have found that RRM2 plays a crucial role in cell death, affecting autoimmune disorders such as rheumatoid arthritis (RA), as well as several types of cancer." (PMID 38431869, 2024). "Our results suggest that RRM2 has important value in the diagnosis and treatment of rheumatoid arthritis, expecting it to play a role in the new research breakthrough." (PMID 36717858, 2023). "Thus, we boldly conclude that RRM2 is abnormally highly expressed in rheumatoid arthritis samples and its pharmacological blockade can attenuate chondrocyte ferroptosis in vitro." (PMID 36717858, 2023).
Sepsis (3 papers, 2021 to 2025). Sepsis is defined as life-threatening organ dysfunction caused by a dysregulated host response to infection. "This is also the first time that we reported the studies on RRM2, TK1, and TYMS in sepsis." (PMID 35082972, 2022).
amyotrophic lateral sclerosis (2 papers, 2012 to 2018). Amyotrophic lateral sclerosis (ALS) is a neurodegenerative disease characterized by progressive muscular paralysis reflecting degeneration of motor neurons in the primary motor cortex, corticospinal tracts, brainstem and spinal cord. "TDP‐43 has two RNA binding domains (RRM1 and RRM2) and a C‐terminal low complexity glycine‐rich domain (LCD), in which mutations causative for amyotrophic lateral sclerosis (ALS) are clustered." (PMID 29764981, 2018). "Accumulating evidence suggests that pathogenic TAR DNA-binding protein (TDP)-43 fragments contain a partial RNA-recognition motif domain 2 (RRM2) in amyotrophic lateral sclerosis (ALS)/frontotemporal lobar degeneration." (PMID 23300771, 2012).
asthma (2 papers, 2021 to 2022). "Several genes such as SERPINE1, GPRC5A, SFN, ABCA1, MKI67, and RRM2 have been found to be downregulated in severe uncontrolled asthma using PBMCs and, therefore, potential biomarkers." (PMID 36294997, 2022). "Our in silico and in vitro results showed that RRM2 was upregulated in asthmatic bronchial epithelium and fibroblasts, specifically in Th2-high asthma." (PMID 34088958, 2021). "SERPINE1 and GPRC5A were downregulated in the blood of eosinophilic asthmatics, while RRM2 was upregulated in an acute attack of asthma." (PMID 34088958, 2021). "Interestingly, only RRM2 was upregulated in the acute/exacerbation phase of asthma and returned to the basal level when the attack subsides." (PMID 34088958, 2021). "Our in-silico analysis showed that RRM2 mRNA expression was upregulated in the blood of an asthmatic patient who had upper respiratory tract infections and those who have acute exacerbation of asthmatic attack but was downregulated in those with severe asthma and wheezes." (PMID 34088958, 2021). "Validation of the gene expression in PBMC of locally recruited asthma patients showed that SERPINE1, GPRC5A, SFN, ABCA1, MKI67, and RRM2 were downregulated in severe uncontrolled asthma." (PMID 34088958, 2021). "ABCA1 and RRM2 expression were lower in severe asthmatics than nonsevere asthmatics and healthy controls, making them potential biomarkers to differentiate the asthma severity." (PMID 34088958, 2021).
breast invasive carcinoma (2 papers, 2019 to 2023). "The analysis of the expression of RRM2, CDC6, and TOP2A in normal and tumour breast invasive carcinoma using GEPIA showed significant increased expression of RRM2, CDC6 and TOP2A in tumour samples as compared to normal tissue." (PMID 36997866, 2023).
colitis (2 papers, 2016 to 2024). Inflammation of the colon. "A PPI network based on DEGs was constructed using STRING, and a highly interconnected cluster was identified as a potential functional molecular complex of colitis, including 8 hub genes, that is, NDC80, PBK, CEP55, RRM2, ASPM, NCAPG, TOP2A, and CDKN." (PMID 38661103, 2024).
colorectal adenoma (2 papers, 2016 to 2021). An adenoma that arises from the colon or rectum. "Furthermore, the mRNA levels of RRM2 were increased both in colorectal adenomas and carcinomas and maintained upregulations in all CRC TNM stages compared to the adjacent normal tissues." (PMID 34234118, 2021). "As expected, the expression correlation between RRM2 and MYBL2 was significantly strengthened in the colorectal adenoma and carcinoma tissues accordingly." (PMID 34234118, 2021).
colorectal tumors (2 papers, 2016 to 2020). "RRM2 and UMPS upregulations and DPYD downregulation in colorectal tumors comply with the previous study." (PMID 27733154, 2016). "On the basis of our gene expression data we may generalize, that colorectal tumors irrespective of the stage and localization share common downregulation of DPYD and upregulation of PPAT, UMPS, RRM2, and SLC29A1 transcripts." (PMID 27733154, 2016).
endometriosis (2 papers, 2021 to 2024). The growth of functional endometrial tissue in anatomic sites outside the uterine body. "One of them is a recent large-scale bioinformatic analysis of previously available microarray datasets, where authors reported RRM2 being downregulated in endometriosis lesions compared to healthy endometrial tissue in the uterus." (PMID 34683911, 2021). "Since we suggested RRM2 as a novel target for endometriosis therapy, we aimed to further investigate the effect of its downregulation to the cells." (PMID 34683911, 2021). "In order to test the therapeutic potential of RRM2 downregulation in different types of endometriosis, cell cycle analysis of transfected endometriotic primary cells was carried out." (PMID 34683911, 2021). "Bearing this in mind and in light of the results of this study, we believe RRM2 is vital for endometriosis lesion growth and, therefore, has high potential as a gene target for endometriosis therapy." (PMID 34683911, 2021). "Relying on the similarities described for cancer and endometriosis, we postulated that RRM2 could be suitable for developing endometriosis therapeutics as well." (PMID 34683911, 2021). "Therefore, the potential role of silencing ribonucleotide reductase subunit M2 (RRM2) in endometriosis therapy has been investigated in this work, in addition to VEGF-A as a therapeutic siRNA target." (PMID 34683911, 2021). "We suggest a novel target, RRM2, for endometriosis therapy and as a proof-of-concept, we propose a CPP-mediated gene therapy approach for endometriosis and cancer." (PMID 34683911, 2021).
Fanconi anemia (2 papers, 2013 to 2024). Fanconi anemia (FA) is a hereditary DNA repair disorder characterized by progressive pancytopenia with bone marrow failure, variable congenital malformations and predisposition to develop hematological or solid tumors.
leiomyosarcoma (2 papers, 2017 to 2020). An uncommon, aggressive malignant smooth muscle neoplasm, usually occurring in post-menopausal women. "Supportively, an HDAC inhibitor, mocetinostat, has been found to reduce RRM2 expression in human leiomyosarcoma cells." (PMID 31936661, 2020). "The roles of RRM2 and hENT1 in the context of gemcitabine resistance in leiomyosarcoma have yet to be identified, and are currently under study in our laboratory." (PMID 29186204, 2017).
Lymphadenopathy (2 papers, 2023 to 2024). Enlargement (swelling) of a lymph node. "In our study, higher RRM2 mRNA levels were associated with the absence of lymphadenopathy and a Rai stage of 0, which also could suggest a favorable prognosis profile, and be supported by our hypothesis regarding RRM1." (PMID 36811764, 2023). "Significantly higher RRM2 mRNA levels were reported in patients without lymphadenopathy (p = 0.048) and Rai stage 0 (p = 0.025)." (PMID 36811764, 2023). "Moreover, the finding of a correlation between methylation status and the presence of lymphadenopathy is very interesting, as lymphadenopathy is an important feature of CLL, and has also been related both with RRM1 and with RRM2 mRNA expression in our study, which make RNR a possible biomarker." (PMID 36811764, 2023).
medulloblastoma (2 papers, 2017 to 2024). A malignant, invasive embryonal neoplasm arising from the cerebellum. "The expression level of RRM2 is significantly higher in medulloblastoma tissues than in normal tissues." (PMID 40625451, 2024). "The crucial role of ribonucleotide reductase M2 (RRM2) enzyme in cancer occurrence and progression has been well‐established, but its specific function and significance in medulloblastoma (MB) remains largely unknown." (PMID 40625451, 2024). "previously identified RRM2 as a key gene in medulloblastoma through bioinformatics analysis, but they did not conduct any related experimental validation." (PMID 40625451, 2024).
Obesity (2 papers, 2018 to 2020). Accumulation of substantial excess body fat. "Specifically, the expression of RRM2 in extreme weight was higher than extreme obesity (P=0.0224)." (PMID 32922202, 2020).
ovarian endometriosis (2 papers, 2023). A non-neoplastic disorder characterized by the growth of endometrial tissue in the ovaries. "It is also suspected that RRM2 upregulation may promote cell invasion and metastasis in cancer and ovarian endometriosis." (PMID 38069001, 2023).
papillary renal cell carcinoma (2 papers, 2019 to 2021). A rare subtype of renal cell carcinoma, arising from the renal tubular epithelium and showing a papillary growth pattern, which typically manifests with hematuria, flank pain, palpable abdominal mass or nonspecific symptoms, such as fatigue, weight loss or fever. "A 3-mRNA signature consisting of ERG, RRM2, and EGF was constructed to predict survival in papillary renal cell cancer with satisfactory accuracy." (PMID 31886185, 2019).
Skin Cutaneous Melanoma (2 papers, 2021 to 2024). "Furthermore, other studies reported that CCNF (an E3 ligase) targets RRM2 (Ribonucleotide reductase M2), a pro-tumorigenic protein, which is linked to poor survival rate in patients with skin melanoma and associated with its protein degradation activity." (PMID 34201347, 2021).
squamous cell carcinoma (2 papers, 2015 to 2023). A carcinoma arising from squamous epithelial cells. "However, RRM2 serum levels were higher in adenocarcinoma patients than in squamous cell carcinoma patients, which is inconsistent with gene expression data from the GEPIA database." (PMID 37699023, 2023). "For expression levels by histology, we found that squamous cell carcinomas tended to have higher levels of both RRM1 (p < 10–5) and RRM2 (p < 10–5 cytoplasmic and nuclear) than adenocarcinomas." (PMID 26001082, 2015).